PLIN2 (perilipin 2)
Diseases named in the same sentence as PLIN2 in open-access papers (continued):
Sharing a sentence is not in itself a finding about the gene and the disease.
breast carcinoma (22 papers, 2008 to 2025). "For example, PLIN2 expression is upregulated in liver cancer, renal cell carcinoma, oral squamous carcinoma, and breast cancer and is associated with poor prognosis." (PMID 40640171, 2025). "High expression of PLIN2 was found to be an unfavorable factor for OS in breast cancer and was associated with aggressive tumor behavior." (PMID 37189627, 2023). "Querying the Kaplan–Meier plotter, we observed a significant negative correlation between lipid droplet associated protein PLIN2 expression level and relapse-free survival in breast cancer patients." (PMID 31905780, 2019). "Indeed, it has been previously reported that LD expansion (revealed by increased levels of the LD-associated protein, perilipin 2) is negatively correlated with relapse-free survival in patients with breast cancer." (PMID 36614209, 2023). "LD marker PLIN2 is strongly associated with poor overall survival in breast cancer patients." (PMID 35545051, 2022). "We measured the positivity of each core for PLIN2 expression in cores representing progression of breast cancer." (PMID 35545051, 2022). "Further, we used immunohistochemistry to assess the levels of PLIN2 in human breast cancer tissue arrays compared with normal breast tissue." (PMID 35545051, 2022). "On the one hand, high expression of PLIN2 was associated with poor MFS, DFS, and OS rates in cutaneous melanomas and related to poor prognosis in pancreatic ductal adenocarcinoma, breast cancer, and lung adenocarcinomas." (PMID 35372038, 2022). "For this, we stained a breast cancer progression microarray containing 199 cores, representing different stages of breast cancer, with anti-PLIN2 antibody." (PMID 35545051, 2022). "As an example, mammary gland has been reported to produce PLIN2, and breast cancers characterized by elevated expression of PLIN2 result more aggressive." (PMID 33735111, 2021). "In both breast cancer and leiomyoma human cell lines, the PLIN2 gene has a PGR response element in its promoter region." (PMID 23663413, 2013). "RU486 (10−6 M) treatment for 6 hours increased PLIN2 expression in T47D breast cancer cells and leiomyoma cells." (PMID 22272226, 2012). "The greatest induction in PLIN2 expression was observed at 10−7 M RU486 in T47D breast cancer cells and 10−5 M RU486 in leiomyoma cells." (PMID 22272226, 2012). "Overexpression of PLIN2 has been reported in various tumors, including Burkitt lymphoma, malignant melanoma, renal cell carcinoma, lung adenocarcinoma, and breast cancer." (PMID 41041279, 2025). "Furthermore, 34.4% of the proteins were reported to be associated with other cancers, including macrophage-capping protein (CAPG), which is a as breast cancer biomarker, and perilipin-2 (PLIN2), which is a renal cell carcinoma biomarker." (PMID 32675193, 2020). "Next, we set out to investigate whether PLIN2 expression correlates with an increase in lipid droplet number across a panel of breast cancer cell lines." (PMID 31905780, 2019). "Spatial distribution of PLIN2 found in D-17 and COS4288 3D model located to the hypoxic area in the middle of the spheroids is in accordance with previous observations, describing increased PLIN2 protein levels associated with necrotic regions of human breast carcinoma." (PMID 35834072, 2022). "In breast cancer, the high expression of PLIN1 correlated with a good prognosis, but PLIN2 and PLIN4 expression correlated with a poor prognosis." (PMID 37998612, 2023). "In breast cancer, high expression of PLIN1 predicted a longer overall patient survival, while overexpression of PLIN2 indicated poor overall patient survival." (PMID 35834072, 2022). "Therefore, we asked whether PLIN2 over-expression has any prognostic value in breast cancer." (PMID 31905780, 2019). "Enhanced expression of PLIN2 correlated with disease progression, from ductal carcinoma in situ (DCIS) to invasive ductal carcinoma and to lymph node macrometastases (p = 0.0008) and for advanced stages of breast cancer (p = 0.001)." (PMID 35545051, 2022).
breast carcinoma (continued). "Querying the Kaplan–Meier plotter, we have found a significant negative correlation between PLIN2 expression and relapse-free survival in breast cancer patients." (PMID 31905780, 2019). "It is suggested that elevated expression of TPT1, PLIN2 and FABP3 might play a role in suppressing goat mammary tumor formation." (PMID 30009039, 2018).
clear cell renal cell carcinoma (15 papers, 2012 to 2025). "A similar approach performed in clear cell renal cell carcinoma (ccRCC) revealed that PLIN2 upregulation is associated with a good disease prognosis, while PLIN2 knockdown in human kidney carcinoma A-498 cells favors proliferation, migration, and invasion of ccRCC cells." (PMID 34067931, 2021). "High PLIN2 expression is associated with better cancer-free survival in clear cell renal carcinoma." (PMID 22272226, 2012). "In clear cell renal cell carcinoma (ccRCC), PLIN2 was elevated in tumors and correlated with HIF-2α." (PMID 35372038, 2022). "However, in colorectal cancer, lung adenocarcinoma, renal clear cell carcinoma, and pancreatic ductal adenocarcinoma, PLIN2 was mainly expressed in TCs." (PMID 35372038, 2022). "Interestingly, HIF-2α—but not HIF-1α—promotes PLIN2 gene overexpression in clear-cell renal cell carcinoma, and perilipin-2 accumulation in these cells was associated with increased cancer cell viability." (PMID 32029741, 2020). "Plin2 was significantly upregulated (p < 0.05) in glioblastoma multiforme (GBM), clear cell renal cell carcinoma (KIRC) and thyroid cancer (THCA)." (PMID 37047411, 2023).
diabetes (15 papers, 2013 to 2025). "We show that exposure of naive human Mos to heat-inactivated plasma from patients with diabetes or to FFAs was sufficient to induce PLIN2 expression and secretion of DR-associated inflammatory cytokines." (PMID 37781924, 2023). "Clinical studies have shown that the polymorphism rs4578621 in the Perilipin(PLIN) gene is associated with type 2 diabetes mellitus, and the expression of Perilipin 2(PLIN2) is upregulated in the kidneys of diabetic db/db mice,which may be the reason." (PMID 38742197, 2024). "Importantly, APOC3 ASO treatment reduced diabetes-associated glomerular hypertrophy, glomerular perilipin 2 staining, macrophage accumulation, and lipid-loaded macrophage accumulation." (PMID 38743496, 2024). "Exposure of naive Mos to hi-plasma from patients with diabetes or PA was sufficient to induce PLIN2 expression and trigger long-term expression of DR-related proinflammatory cytokines." (PMID 37781924, 2023). "This encouraged us to analyze the relationship between pre-existent diabetes and PLIN2 serum levels." (PMID 34572396, 2021). "Genetic ablation of Plin2 in Akita mice leads to mitigation of ER stress, forestalling β cell apoptosis, partially restoring β cell mass, and ameliorating diabetes." (PMID 28102311, 2017). "Furthermore, lipids appeared to accumulate intracellularly as perilipin 2 (a lipid droplet marker that is increased with lipid accumulation) staining was also increased in the setting of diabetes." (PMID 38743496, 2024). "Additionally, elevated expression of PLIN2 was observed in human islets obtained from donors with type 2 diabetes mellitus." (PMID 39192017, 2024). "In fact, PLIN2 is increased in skeletal muscle from rats with genetic-induced diabetes, which might be considered as a compensatory mechanism to deal with excessive lipid load." (PMID 28676863, 2017). "For example, certain proteins, such as PLIN2, require phosphorylation to become CMA substrates, whereas others, like phosphoprotein enriched in diabetes (PED), are degraded only in their unphosphorylated state." (PMID 41249047, 2025). "Smoking status, diabetes, hypertension, dyslipidemia, and MetS did not considerably influence PLIN2 concentrations." (PMID 41515601, 2025). "The impact of PPARδ upregulation was further manifested by a significant increase in cell foaming, as evidenced by elevated PLIN2 protein expression in patients with diabetes compared to those without." (PMID 38989454, 2024). "Lipid-laden macrophages have been reported in the retina following blood-retina barrier breakdown, but the localization of PLIN2+ MPs in the diabetic retina has not been reported thus far." (PMID 37781924, 2023). "Identifying these signaling pathways as targets for Plin2 in ISCs is in agreement with our previous study and other reports, showing that the Smad-TGF-β pathway could be activated in ISCs from patients with diabetes." (PMID 35845956, 2022). "Of note, serum PLIN2 concentrations were independent of the presence of diabetes." (PMID 34572396, 2021). "No PLIN2+ cells were observed in regions without microaneurysms in the diabetes mellitus (DM) retina, nor were these cells found in the control patient’s retina (data not shown)." (PMID 37781924, 2023).
hepatocellular carcinoma (13 papers, 2013 to 2026). A malignant tumor that arises from hepatocytes. "In hepatoma cells, an LD consists mainly of TGs surrounded by a phospholipid monolayer and proteins associated with the LD surface, including perilipin 2 (PLIN2)." (PMID 35742827, 2022). "PLIN2 has been shown to be a major LD surface protein in HuH7 hepatoma cells, and overexpression of PLIN2 causes LD accumulation in cells." (PMID 35742827, 2022). "Here, we identify serine/threonine kinase NEK2A as a negative regulator of PLIN2 expression in human hepatoma cells." (PMID 42291266, 2026). "In hepatocellular carcinoma, PLIN2 shows a trend of high expression and correlates with poor prognosis; however, in uterine smooth muscle tumors, low expression of PLIN2 reprograms the cells to a hyperproliferative phenotype." (PMID 38779100, 2024). "Induction of perilipin 2 is typically augmented in LD biogenesis as observed in cultures of primary human hepatocytes and the hepatoma cell lines." (PMID 30547786, 2018). "Lipid droplets in hepatoma cells can also be detected by staining with antibodies directed against adipose differentiation-related protein (ADRP)/perilipin 2, that is strongly expressed in liver cells and associates with lipid droplets." (PMID 25019511, 2014). "In hepatocellular carcinoma (HCC), overexpression of PLIN2 promotes cell proliferation, potentially by inhibiting the degradation of HIF1α, which facilitates HCC cell proliferation." (PMID 39834787, 2024). "PLIN2 inhibits the adenosine 5′-AMPK/ULK1 (human) recombinant protein-lysosome pathway and promotes cell proliferation in hepatocellular carcinoma (HCC)." (PMID 39588271, 2024). "Additionally, recent evidence in hepatocellular carcinoma cells suggests that glucose starvation promotes the phosphorylation of PFKL, which facilitates its binding to Plin2." (PMID 40825999, 2025).
gastric cancer (11 papers, 2021 to 2025). A primary or metastatic malignant neoplasm involving the stomach. "As for PLIN2, in gastric cancer and aggressive melanoma (IM), PLIN2 overexpression cells were significantly associated with promoting cell proliferation and metastasis." (PMID 35372038, 2022). "For example, RNA-seq analysis indicated PLIN2 was an indispensable gene in the suppression of ferroptosis caused by abnormal lipometabolism in gastric carcinoma." (PMID 34692796, 2021). "Perilipin-2 may be involved in gastric cancer progression by regulating abnormal lipid metabolism and ferroptosis; polyunsaturated fatty acid biosynthesis pathway is associated with ferroptosis sensitivity of gastric carcinoma cells." (PMID 38503948, 2025). "Increased PLIN2 expression reduces oxidative stress and alters lipid metabolism in fibroblasts and gastric cancer cells." (PMID 40082867, 2025). "In recent years, dysregulation of PLIN2 expression has been confirmed in a variety of cancers and is correlated with patient survival, including gastric cancer and renal cell carcinoma." (PMID 41408408, 2025). "In gastric cancer, PLIN2 alleviates the metabolic abnormality of FAs, inhibits the ferroptosis process in gastric cancer cells, and enhances proliferation." (PMID 41421797, 2025). "Recent studies have shown that PLIN2 plays pivotal roles in the regulation of ferroptosis induced by abnormal lipid metabolism in gastric cancer." (PMID 35100981, 2022). "Consistent with our transcriptomic findings, LGALS9 treatment upregulated the expression of genes involved in cholesterol metabolism (NPC2, APOA) and PPAR signalling (SCD, PLIN2, FABP1), suggesting that LGALS9‐P4HB interaction modulates lipid metabolism in gastric cancer cells." (PMID 40534096, 2025).
renal cell carcinoma (11 papers, 2017 to 2025). "In renal cell carcinoma, PLIN2 expression was correlated with a favorable prognosis, but the high expression of PLIN3 is correlated with a poor prognosis." (PMID 37998612, 2023). "Given the evidence from clinical studies, some studies have begun to explore the molecular mechanism of PLIN2 in renal cell carcinoma." (PMID 36439875, 2022). "Previous studies have demonstrated the role of PLIN2 as a tumor marker in different body fluids or in tumor tissue for several malignant diseases, such as renal cell carcinoma, colorectal carcinoma or lung adenocarcinoma." (PMID 34572396, 2021). "Transcriptional profiling of primary renal cell carcinoma revealed a correlation between HIF-2α (but not HIF-1α) and high expression of the lipid droplets coat protein perilipin 2 (PLIN2)." (PMID 34071836, 2021).
lung adenocarcinoma (8 papers, 2021 to 2025). A carcinoma that arises from the lung and is characterized by the presence of malignant glandular epithelial cells. "A pathological study found that PLIN2-positive lung adenocarcinoma was associated with a worse outcome reflected in overall and disease-free survival." (PMID 36439875, 2022).
type 2 diabetes (8 papers, 2013 to 2024). "The human gene region that includes PLIN2 is strongly associated with plasma cholesterol levels (p = 1.362e-20; Type 2 Diabetes Knowledge Portal." (PMID 34387191, 2021). "In addition, we observed that people with type 2 diabetes have a higher myocellular PLIN2 protein content than endurance-trained athletes." (PMID 32529413, 2020). "Interestingly, PLIN2 protein content is higher in cases where there is increased IMTG content, such as in females, type II diabetics, and with endurance training." (PMID 24303154, 2013). "In accordance with a recent observation in myotubes from obese individuals with or without type 2 diabetes, we could not detect any change in expressions of PLIN2 and PLIN3, and further investigation on how PLINs and lipases interact is needed." (PMID 25790476, 2015).
colorectal cancer (6 papers, 2019 to 2025). A primary or metastatic malignant neoplasm that affects the colon or rectum. "Another study conducting plasma proteome analysis found elevated expression of PLIN2 in colorectal cancer patient plasma, even in those with low-grade tumors, indicating that PLIN2 is a sensitive and dependable biomarker in this cancer type 92." (PMID 36439875, 2022). "For instance, in colorectal cancer PLIN2 promotes macrophage polarization towards the M2 phenotype and activates the CD36-dependent epithelial-mesenchymal transition (EMT) pathway in colorectal cancer cells, thereby enhancing tumor invasiveness." (PMID 41246346, 2025).
dyslipidemia (6 papers, 2015 to 2025). "DNA microarray analysis was used to investigate the kidney expression of four genes (Cyp24a1, Plin2, Calb1 and Usp2), which are reported to be involved in metabolic syndrome and LSRD." (PMID 33383715, 2020). "PLIN2 has been investigated in the context of metabolic syndrome and inflammatory diseases, especially in macrophages, adipocytes and hepatocytes; however, the regulation and the role of PLIN2 in microglia are still unknown." (PMID 26367267, 2015). "Despite the strong clinical association, the presence of specific comorbidities (HT, T2D), and dyslipidemia) did not significantly affect serum PLIN2 levels in the NAFLD patient group." (PMID 41515601, 2025).
sarcopenia (6 papers, 2013 to 2024). Progressive decline in muscle mass due to aging which results in decreased functional capacity of muscles. "We have previously reported that PLIN2 in skeletal muscle is increased in old persons, particularly in physically inactive ones and is associated with muscle atrophy and sarcopenia." (PMID 33735111, 2021). "In previous studies, we observed that high levels of PLIN2 in both humans and mice are associated with skeletal muscle atrophy and sarcopenia." (PMID 33735111, 2021). "Consistent with our findings, upregulation of perilipin 2 was shown to be associated with the expression of the muscle atrophy-related gene, MuRF-1, suggesting a role for perilipin 2 in sarcopenia." (PMID 34064680, 2021). "In humans, high levels of perilipin 2 are present in patients with sarcopenia and hepatic steatosis." (PMID 29387723, 2017). "Furthermore, recent data suggested a possible connection between PLIN2, muscle weakness and age-related sarcopenia via a mechanism of excessive intramuscular triglyceride storage." (PMID 34572396, 2021). "Previous work speculated on age-dependent changes of PLIN2 expression and linkage to sarcopenia." (PMID 34572396, 2021). "Although our hypothesis that PLIN2 associates with sarcopenia was not proven, this independency might further strengthen PLIN2′s role as a potential biomarker for multiple organ dysfunction." (PMID 34572396, 2021). "Of note, previous studies assessed Plin2 expression in skeletal muscle whereas, to the best of our knowledge, PLIN2 was not assessed as a serum biomarker in the context of muscle weakness or sarcopenia yet." (PMID 34572396, 2021).